FAM90A20 (family with sequence similarity 90 member A20)
Synonyms: FAM90A20P
Tractability: No criterion of Open Targets' tractability assessment is met for any kind of drug.
Gene: Protein-coding gene on chromosome 8 (7,295,014 to 7,298,024, forward strand). Ensembl gene ENSG00000233295.
Subcellular location (Human Protein Atlas): Nucleoplasm; Nucleoli
Homologues: Orthologues: mouse Fam90a1b (28% identical), mouse Fam90a1a (27% identical), rat Fam90a1l1 (26% identical). Paralogues in human: FAM90A14 (95% identical), FAM90A15 (95% identical), FAM90A3 (95% identical), FAM90A11 (95% identical), FAM90A13 (95% identical), FAM90A5 (95% identical), FAM90A16 (94% identical), FAM90A17 (94% identical), FAM90A23 (94% identical), FAM90A24 (94% identical), FAM90A9 (94% identical), FAM90A10 (94% identical), and 9 more.